AQP4 (aquaporin 4)
Diseases named in the same sentence as AQP4 in open-access papers (continued):
Sharing a sentence is not in itself a finding about the gene and the disease.
Autoimmunity (continued). "Notably, the observed neuroimaging abnormalities, together with the improvement of affective symptoms following immunotherapy, suggest a potential association among AQP4-IgG-mediated autoimmunity, demyelination-like central nervous system lesions, and affective dysregulation." (PMID 41586066, 2026). "A possible hypothesis for MOG and AQP4 antibody-associated autoimmunity triggered by a VZV infection is that the VZV infection causes a breakdown of the blood-brain barrier, as indicated by the common finding of an elevated CSF/serum albumin ratio in herpes zoster." (PMID 34737756, 2021). "The conclusion from this group was that these observations provide further support for the hypothesis that astrocytic impairment associated with humoral autoimmunity directed against AQP4, which causes AQP4 downregulation, is the primary immunopathogenic mechanism in NMO." (PMID 22363840, 2012). "While NMOSD pathogenesis is mediated by aquaporin-4 antibody (AQP4-IgG) autoimmunity, increasing evidence suggests significant comorbidity with affective symptoms." (PMID 41586066, 2026). "In contrast, AID appear less common in MOGAD, where the prevalence of autoimmunity is generally lower than in AQP4-NMOSD." (PMID 40495001, 2025). "Autoimmunity directed against AQP4 affected overlapping and distinct CNS niches as compared with autoimmunity directed against MOG." (PMID 39934927, 2025). "Variable changes of AQP1 and AQP4 were found in biopsied CNS samples compared with normal controls reflecting the astrocytic reactions to stress within the context of GFAP autoimmunity." (PMID 38310187, 2024). "In NMOSD, the target antigen of autoimmunity is the water channel aquaporin 4 (AQP4) densely expressed on the astrocytic foot processes at the blood-brain barrier." (PMID 37397465, 2023). "Overall, signs of co-existing autoimmunity have been reported in 25–40% of patients with AQP4-IgG-positive NMOSD in some cohorts." (PMID 37022481, 2023). "Our study suggests that Tfh cells contribute to the pathophysiology of NMOSD-like disease in a mouse model with AQP4 autoimmunity induced by AQP4 immunization." (PMID 36649074, 2023). "Here, we developed a mouse model of NMOSD with AQP4 autoimmunity using electroporation-mediated immunization." (PMID 36649074, 2023). "AQP4-IgGs are directly pathogenic, and patients with NMOSD who are seropositive for these autoantibodies have underlying AQP4 autoimmunity." (PMID 36649074, 2023). "A previous study of MRI findings in the CNS and aquaporin-4 autoimmunity showed that 29% of the patients presented with extensive hemispheric effects that were related to high Ab titres and cerebral deep white matter (58%)." (PMID 37208665, 2023). "Investigation of AQP4 and astrocytes as targets of AQP4-IgG-mediated autoimmunity showed differences between AQP4-IgG and MOG-IgG EAE at acute disease stage." (PMID 37499337, 2023). "Our study provides a novel mouse model of NMOSD with AQP4 autoimmunity in which Tfh cells contribute to its pathophysiology." (PMID 36649074, 2023). "First, serum AQP4-IgG levels are ∼1,000-fold higher than in cerebrospinal fluid, supporting peripheral initiation of AQP4-directed autoimmunization." (PMID 35666871, 2022). "In AQP4-IgG seropositive patients a wide spectrum of autoimmune disorders was recognized, hence the use of the term NMO spectrum disorders (NMOSD)." (PMID 35454978, 2022). "In silico modeling indicates that HLA molecules within these haplotypes are predicted to bind AQP4 at several sites, potentially contributing to the development of autoimmunity." (PMID 36268024, 2022). "Yet, both ANA and coexistence of other autoimmune conditions have been described to be a potential help in differentiation vs AQP4‐IgG positive NMOSD." (PMID 33047894, 2021). "The NMOSD diagnostic criteria have been revised several times during the last two decades, mainly due to improved understanding of AQP4 autoimmunity." (PMID 31187587, 2019).
Autoimmunity (continued). "The age distribution was suggested to influence the AQP4 autoimmunity where females aged 65 years above were more likely to be seropositive than other age groups, and the detection rate of AQP4-IgG rise exponentially in females after 50 years old." (PMID 31803011, 2019). "Specifically, antinuclear antibodies were found in only 7% of MOG-IgG patients (versus 43% of AQP4-IgG patients), and coexisting autoimmune conditions were reported in only 11% of MOG-IgG individuals (versus 45% of AQP4-IgG subjects) in another series." (PMID 29670575, 2018). "This was also observed in the Korean, Thai, and Japanese studies, suggesting heterogeneity of AQP4 autoimmunity." (PMID 28203460, 2017). "The pathogenetic mechanisms triggering AQP4 autoimmunity is uncertain, but B cells certainly play important roles." (PMID 29387055, 2017). "It was previously shown that brain lesions with AQP4 autoimmunity in patients with NMOSD are accompanied by discontinued vasogenic edema." (PMID 28293214, 2017). "Coexisting autoimmunity in MOG-IgG-positive NMOSD seems to be rare compared with AQP4-IgG-positive NMOSD." (PMID 27793206, 2016). "This is in line with a previous study that reported a lower frequency of concomitant autoimmune disorders in ‘AQP4-IgG-seronegative’ NMOSD patients." (PMID 27793206, 2016). "Coexisting autoimmune disorders are present in more than one third of AQP4-IgG-positive NMOSD patients." (PMID 27793206, 2016). "Previous NMO studies suggested that the variable vulnerability to AQP4 autoimmunity depended on the tissues involved." (PMID 25259647, 2014). "Brain MRI abnormalities in AQP4 autoimmunity are typically localized in the periependymal regions, where AQP4 is highly expressed." (PMID 23259063, 2012). "Based on the literature, autoantibodies were also tested against six potential organ–specific antigens implicated in T1D and/or other autoimmune conditions including ATP4B, TGM2, TPO, KCNRG, AQP-4, and GFAP." (PMID 23028856, 2012). "To evaluate their potential role in CNS autoimmunity, we have identified and characterized T cells that respond to AQP4 in C57BL/6 and SJL/J mice, two strains that are commonly studied in models of CNS inflammatory diseases." (PMID 21151500, 2010). "IgM, as well as isotype-switched antibodies specific for naturally expressed AQP4, should be evaluated in more patients with autoimmunity and NMO." (PMID 18510734, 2008). "Comorbid autoimmunity, particularly AQP4-IgG co-positivity or systemic autoimmune features, may further diminish the treatment response." (PMID 40717732, 2025). "hypothesize that the temporal association of organizing pneumonia with the onset of AQP4-IgG seropositive NMOSD in their patients suggests that the lung, muscle, and neurological involvement might be a single disease entity induced by AQP4-IgG autoimmunity." (PMID 41562061, 2025). "Based on these, we formulated a speculative model of NMOSD pathogenesis focused on the upstream inflammatory pathway for AQP4 autoimmunity: AQP4-IgG and AQP4 protein-conjugating AQP4-immunocomplexes bind primarily to CD16A on NKT cells." (PMID 38326464, 2024). "Together, these findings may offer new insights into AQP4 autoimmunity, and advance NKTfh as a potential new therapeutic target." (PMID 38326464, 2024). "Finally, we provided insight into an early phase of GFAP autoimmunity in an autopsy of a pug dog encephalitis that was characterized by marked meningoencephalitis with selective astrocytic damage with loss of GFAP and AQP4 in the lesions." (PMID 38310187, 2024). "More accurate evaluation of AQP4 autoimmunity may be facilitated by adding AQP4-immunocomplexes, complement, and specific cytokine stimuli to the system to simulate the phenomena occurring in the NMOSD patients." (PMID 38326464, 2024). "Our study suggests that AQP4 might be instrumental for the efficient re-establishment of homeostatic fluid management in the retina during CNS autoimmunity." (PMID 35536323, 2022).
Autoimmunity (continued). "In this review article, we will discuss the radiological features of spinal cord involvement in autoimmune disorders such as MS, AQP4+NMOSD, myelin oligodendrocyte glycoprotein antibody-associated disease (MOGAD), and other recently characterized immune-mediated diseases." (PMID 36330423, 2022). "Memory B cells (Bmems) specific for AQP4 are likely crucial in AQP4 autoimmunity." (PMID 34445343, 2021). "However, according to other publications, the relative increase in the prevalence of patients with both AQP4-NMOSD and AChR-MG suggests that these patients have a predisposition to autoimmunity, but the dynamics of the individual diseases remain unchanged." (PMID 34439676, 2021). "The prevalence and incidence estimates were comparable to that of a population‐based study in Olmsted County, Minnesota, USA, which compared the population‐based seroprevalence and seroincidence of AQP4‐IgG autoimmunity among patients with an IDD in two ethnically divergent populations (2003–2011)." (PMID 31187587, 2019). "The AQP4 antibody binds to the extracellular surface of the AQP4 receptor in the three-dimensional form of the epitopes rather than their linear form, a pattern that is typical in human autoimmune disorders." (PMID 29064441, 2017). "Accordingly, the expression of complement-regulatory protein or EAAT2 in the involved tissue may affect selective vulnerability to AQP4 autoimmunity." (PMID 25259647, 2014). "Several patients with symptoms similar to idiopathic hypersomnia were reported to have neural-specific anti-AQP4 antibody, and this organ-specific autoimmunity might be compatible with our findings of a Th1 involvement in idiopathic hypersomnia." (PMID 20221267, 2010). "As salivary glands express AQP4, the initiating autoimmune response to non-AQP4 antigens might liberate AQP4 that because of intrinsic failures in immune regulation in autoimmunity would facilitate AQP4 B cell activation and survival." (PMID 18510734, 2008). "It is widely believed that NMOSD pathogenesis is driven by autoimmunity against AQP4 in astrocytes; however, the relevant self-Ag(s), i.e., various epitopes in AQP4 and non-AQP4 of astrocyte Ags, in NMOSD remain speculative, with the possibility that these Ags differ among patients." (PMID 41497588, 2025). "In addition, glaucoma-mediated optic nerve damage might lead to release of AQP4 and hence contribute to the development of AQP4 autoimmunity in our first patient." (PMID 29387055, 2017). "Patients often show autoimmunity to AQP4, producing antibodies (NMO-Ab) that bind to the AQP4 protein inducing an inflammatory cascade response that leads to demyelination, cell damage and death." (PMID 34843700, 2022). "Previous studies had shown that coexisting autoimmunity was rare in MOG-ON patients, whereas coexisting autoimmune disorders were present in more than one-third of AQP4-ON patients." (PMID 31061727, 2019). "Infection and autoimmunity can result in events that alter the BBB and thus permit access of AQP4-specific antibodies and T cells to the CNS." (PMID 18510734, 2008). "AQP4-IgG may initiate a primary inflammatory event and disrupt astrocytic function, while GFAP autoimmunity occurs as a secondary phenomenon." (PMID 39949796, 2025). "The clonal expansions of specific T and B cell subsets are no longer abstract markers of autoimmunity; they represent the specific cellular response likely mounted against aquaporin-4 (AQP4) expressed on an occult tumor." (PMID 40963604, 2025). "In fact, no model has achieved spontaneous AQP4 autoimmunity with pathology in optic nerve and spinal cord." (PMID 38129902, 2023). "Although coexisting of MOG-IgG and AQP4-IgG were found in a French cohort study, simultaneous involvement of MOG-IgG in the peripheral nervous system was thought to be unusual, and AQP4-IgG was only found in CSF, casting doubt on the existence of an overlap syndrome in GFAP autoimmunity." (PMID 37205100, 2023).
Autoimmunity (continued). "Our direct comparison in animal models suggests a predilection for ventral neuroinflammatory lesions associated with AQP4-IgG and ventrolateral lesions in purely MOG-targeted autoimmunity regardless of MOG-IgG-augmentation." (PMID 37499337, 2023). "In summary, our study provides evidence for a non-redundant role of AQP4 in retinal integrity in the context of CNS autoimmunity." (PMID 35536323, 2022). "This classical NMO definition may today segregate into AQP4‐IgG, MOG‐IgG and GFAP‐related autoimmunity or double seronegative NMOSD patients." (PMID 31187587, 2019). "AQP4-IgG or MOG-IgG from the systemic circulation may enter the CNS through a disrupted blood–brain barrier, potentially initiating primary inflammatory events and damaging astrocytes, while GFAP autoimmunity may occur as a secondary phenomenon." (PMID 40777035, 2025). "Cerebellar ataxia in NMDAR-E may not be explained by concomitant KLHL11, MOG, AQP-4, or GluK2 autoimmunity." (PMID 39735552, 2024). "This may mimic AQP4‐IgG and MOG‐IgG–related autoimmunity or seronegative NMOSD." (PMID 31187587, 2019). "Screening cell-based immunofluorescence assays revealed a higher frequency of MOG and MuSK autoantibody-positive samples compared with AChR or AQP4 (a total of 12/643 [1.9%], 8/643 [1.2%], 5/643 [0.8%], and 4/643 [0.6%] positive samples in the nonneurologic autoimmunity cohorts, respectively)." (PMID 30824481, 2019). "Patients with long-term AQP4 autoimmunity in the brain in the absence of ON or TM are not common." (PMID 28293214, 2017). "Patients with long-term AQP4 autoimmunity in the brain in the absence of ON or TM were not common." (PMID 28293214, 2017). "It is acknowledged, however, that available animal models of NMO are imperfect, as NMO pathology requires invasive, passive-transfer of AQP4-IgG rather than spontaneous autoimmunity, and because of differences between rodents and humans in astrocyte:neuron ratios and their biology." (PMID 27117475, 2016). "Because these are not areas where AQP4 is highly distributed, it is unknown why these regions are frequently involved in AQP4 autoimmunity." (PMID 23259063, 2012). "Thus the target sequences within AQP4 with which to investigate NMO are beginning to be realized and thus soon will be available to develop AQP4 animal model based on those enumerated and developed for MOG-induced CNS autoimmunity." (PMID 18510734, 2008). "This is also in line with rare cases of MOG-IgG coexisting with other autoantibodies (e.g., AQP4-IgG, NMDAR-IgG) where the clinical-MRI phenotype is typically predicted by the accompanying antibody, although overlapping features may occur (see also “Coexisting autoimmunity” above)." (PMID 35785363, 2022). "Therefore, whether autoimmune AQP4 in the kidney is associated with NMOSD should be examined further, because AQP4-IgG seropositive cases do not meet the present definition of NMOSD, indicating that they may be autoimmune AQP4 channelopathies." (PMID 28293214, 2017). "However, this hypothesis does not explain why AQP4 expressed in peripheral organs does not elicit autoimmunity." (PMID 29312313, 2017). "Considering this finding and the recently increased recognition of brain manifestations in patients with NMOSD, it might be more appropriate to consider that such brain abnormalities are one manifestation of AQP4 autoimmunity rather than a cooccurrence of NMOSD and ADEM or PRES." (PMID 23259063, 2012). "Among all the antibodies with differences, 12 IgG antibodies against Jo-1, SSB, PL-12, PM/scl100, Scl-70, TIF1γ, β-actin, MPO, TTG, AQP4, calprotectin, and CRP were more abundant in patients with autoimmunity than in those without (p < 0.05)." (PMID 38634985, 2024). "In particular, TNF alpha levels have been shown to be elevated in CSF in patients with AQP4 and MOG IgG autoimmunity, but not in patients with MS, and therefore the effect of TNF inhibition is likely different in these CNS inflammatory disorders." (PMID 36247761, 2022).
Autoimmunity (continued). "None of the eight patients tested for SARS-CoV-2 PCR in CSF were positive, and none of the autoantibodies seen in autoimmune forms of encephalitis (NMDAR, LGI1) or encephalomyelitis (AQP4, MOG) were detected in serum or CSF samples." (PMID 32637987, 2020). "Because aquaporin 4 antibodies and myelin oligodendrocyte glycoprotein antibodies were not tested in our patients, an NMO-like autoimmunity could not be completely excluded." (PMID 35370906, 2022).